CT47A6 (cancer/testis antigen family 47 member A6)
Synonyms: CT47.6
Gene: Protein-coding gene on chromosome X (120,958,165 to 120,961,487, reverse strand). Ensembl gene ENSG00000226023.
Subcellular location (Human Protein Atlas): Nucleoli
Homologues: Orthologues: macaque CT47B1 (77% identical). Paralogues in human: CT47A1 (100% identical), CT47A10 (100% identical), CT47A11 (100% identical), CT47A12 (100% identical), CT47A2 (100% identical), CT47A3 (100% identical), CT47A4 (100% identical), CT47A5 (100% identical), CT47A7 (100% identical), CT47A8 (100% identical), CT47A9 (100% identical), CT47B1 (86% identical), and 1 more.